SNX14 (sorting nexin 14)
Description:
Plays a role in maintaining normal neuronal excitability and synaptic transmission. May be involved in several stages of intracellular trafficking (By similarity). Required for autophagosome clearance, possibly by mediating the fusion of lysosomes with autophagosomes (Probable). Binds phosphatidylinositol 3,5-bisphosphate (PtdIns(3,5)P2), a key component of late endosomes/lysosomes. Does not bind phosphatidylinositol 3-phosphate (PtdIns(3P)).
Synonyms: RGS-PX2; SCAR20
Tractability: Antibody: UniProt predicts a signal peptide or a membrane-spanning region. PROTAC: ubiquitination databases record sites on it; its protein half-life has been measured.
Gene: Protein-coding gene on chromosome 6 (85,504,776 to 85,594,156, reverse strand). Ensembl gene ENSG00000135317.
Subcellular location: Lysosome membrane; Late endosome membrane; Cell projection, dendrite
Subcellular location (Human Protein Atlas): Cytosol; Vesicles
Gene Ontology:
Molecular function: phosphatidylinositol-3,5-bisphosphate binding; phosphatidylinositol binding
Biological process: autophagosome maturation; postsynaptic modulation of chemical synaptic transmission
Cellular component: late endosome; late endosome membrane; lysosomal membrane; lysosome; dendrite; postsynapse; synapse
Genetic constraint (gnomAD): Loss-of-function variants: 52 observed, 76.78 expected, observed/expected ratio (o/e) 0.68, 90% interval 0.54 to 0.85. The upper end of that interval is the gene's LOEUF score, 0.85, which puts it in group 3 of 6, group 1 being the genes least tolerant of losing a copy. Missense variants: 619 observed, 735.9 expected, observed/expected ratio (o/e) 0.84, 90% interval 0.79 to 0.9. Synonymous variants: 240 observed, 246.5 expected, observed/expected ratio (o/e) 0.97, 90% interval 0.88 to 1.08.
Gene-disease validity (ClinGen):
ClinGen rates the evidence that SNX14 causes each of these diseases.
autosomal recessive spinocerebellar ataxia 20 (autosomal recessive): Definitive. Any autosomal recessive cerebellar ataxia in which the cause of the disease is a mutation in the SNX14 gene.
Homologues: Orthologues: macaque SNX14 (99% identical), chimpanzee SNX14 (99% identical), guinea pig SNX14 (97% identical), dog SNX14 (97% identical), rat Snx14 (97% identical), mouse Snx14 (97% identical), rabbit SNX14 (95% identical), pig SNX14 (89% identical), tropical clawed frog snx14 (83% identical), zebrafish snx14 (72% identical), Caenorhabditis elegans snx-14 (19% identical). Paralogues in human: SNX25 (17% identical), SNX19 (17% identical), SNX13 (16% identical).
Diseases named in the same sentence as SNX14 in open-access papers:
SNX14 is named in the same sentence as 27 diseases in open-access papers, as found by Europe PMC text mining. Sharing a sentence is not in itself a finding about the gene and the disease. The quoted sentences say what the papers report.
Ataxia (18 papers, 2016 to 2026). Ataxia refers to impaired coordination of voluntary muscle movement. "Homozygous intragenic deletions mediated by Alu–Alu recombination and causing recessively inherited diseases have been reported in BLM, causing Bloom syndrome (MIM 210900), and in SNX14, causing spinocerebellar ataxia (MIM 616354)." (PMID 41438488, 2025). "Research has shown that a higher proportion of patients with early-onset cerebellar atrophy and ataxia carry variants in SNX14 (9.88%) compared to other known pathogenic genes such as GRID2 (2.47%), NPC1 (1.23%), and SETX (1.23%)." (PMID 38655056, 2024). "Knockout mouse models of Snx14 have shown severe motor impairments and cell-autonomous Purkinje cell degeneration, revealing the pathogenic mechanism of cerebellar ataxia." (PMID 38655056, 2024). "Two separate research groups recently identified mutations in the sorting nexin gene SNX14 as the cause of a specific subtype of cerebellar ataxia known as autosomal recessive spinocerebellar ataxia 20 (SCAR20)." (PMID 34308255, 2021). "Loss-of-function mutations in sorting nexin 14 (SNX14) cause autosomal recessive spinocerebellar ataxia 20, which is a form of early-onset cerebellar ataxia that lacks molecular mechanisms and mouse models." (PMID 34691693, 2021). "Although pontine hypoplasia was prominent in our series, cerebellar abnormalities were not as marked as has been reported in pontocerebellar hypoplasia, or SNX14-associated cerebellar ataxia and intellectual disability." (PMID 26917586, 2016). "Additionally, SNX14 deficiency in mice leads to defective axonal mitochondrial transport in Purkinje cells, contributing to cerebellar ataxia, which can be reversed by valproate treatment." (PMID 41277110, 2026). "Furthermore, loss-of-function mutations in Sorting nexin 14 (Snx14), an ER-LD tethering protein, are associated with a form of spinocerebellar ataxia called SCAR20." (PMID 35493070, 2022). "Further studies identified biallelic SNX14 mutations in 12 families with cerebellar atrophy and cerebellar ataxia, displaying altered facial structures and intellectual disability, suggesting that the truncated SNX14 mutations promote lysosomal-autophagosome dysfunction." (PMID 33931804, 2021). "These mutations most often lead to complete loss or truncation of the SNX14 protein, resulting in early onset cerebellar atrophy, ataxia, developmental delay, intellectual disability and coarse facial features, with hearing loss, relative macrocephaly and seizures only reported in some patients." (PMID 32792680, 2020). "Importantly, loss-of-function mutations in SNX14 have recently been described as a cause of a clinically distinguishable recessive syndrome consisting of cerebellar atrophy, ataxia, coarsened facial features, and intellectual disability." (PMID 30473892, 2018). "SNX14 deficiency disrupted microtubule organization and mitochondrial transport in axons by destabilizing the microtubule-severing enzyme spastin, which is implicated in dominant hereditary spastic paraplegia with cerebellar ataxia, and compromised axonal integrity and mitochondrial function." (PMID 34691693, 2021). "On the accelerating rotarod, Snx14-KO mice showed difficulty maintaining balance similar to other cerebellar ataxia mouse models." (PMID 38625743, 2024). "SNX14 deficiency causes a childhood onset cerebellar degeneration syndrome clinically defined as SCAR20 and characterized by cerebellar ataxia and intellectual disability." (PMID 38625743, 2024). "Our study revealed an unprecedented role for SNX14-dependent axonal transport in cerebellar ataxia, demonstrated the convergence of SNX14 and spastin in mitochondrial dysfunction, and suggested valproate as a potential therapeutic agent." (PMID 34691693, 2021). "In summary, our elucidation of SNX14 in the regulation of mitochondrial transport in axons provides new mechanistic insights into the pathogenesis of cerebellar ataxia." (PMID 34691693, 2021).
Ataxia (continued). "Consistent with this, zebrafish ataxia models, such as sorting nexin 14 (snx14) morphants show decreases in PC progenitors while cwf19-like 1 (cwf1911) morphants show disruptions in overall hindbrain morphology." (PMID 27458342, 2016). "At the time of its introduction in 2016, six conditions (EPG5‐related Vici syndrome, WDR45‐related BPAN, SNX14‐related ataxia as well as SPG11‐, ZFYVE26‐, and TECPR2‐related spastic paraplegia) were included with the concept of congenital disorders of autophagy." (PMID 39420677, 2025). "Whereas biallelic mutations in the SNX14 gene are known to cause autosomal recessive spinocerebellar ataxia 20 (SCAR20), a disorder characterized by cerebellar atrophy, ataxia, and severe intellectual disability, mutations in the SNX19 gene have not yet been shown to cause a Mendelian disorder." (PMID 34315878, 2021). "Autosomal Recessive Spinocerebellar Ataxia 20, SCAR20, is a rare condition characterized by intellectual disability, lack of speech, ataxia, coarse facies and macrocephaly, caused by SNX14 variants." (PMID 33193593, 2020). "Cerebellar ataxias are also common among primary autophagy disorders: In addition to global developmental delay, seizures and progressive cerebellar atrophy, children with SNX14-related ataxia (SCAR20) often demonstrate additional multisystem features suggestive of a storage disorder." (PMID 34130600, 2022). "After that, 3 cases of spastic paraplegia were found in patients (No. 2, 22, and 26) with responsible genes including (HACE1, ATL1, AP4M1), respectively, and two cases of cerebellar ataxia in patients (No. 14 and 43), whose responsible genes were SNX14, TDP2, respectively." (PMID 34540776, 2021).
autosomal recessive spinocerebellar ataxia 20 (10 papers, 2020 to 2026). "Loss-of-function mutations in the ER-resident protein Snx14 is the cause of spinocerebellar ataxia autosomal recessive 20 (SCAR20) characterized by intellectual impairment, cerebellar atrophy, ataxia and defective speech development." (PMID 39421023, 2024). "Mutations in the SNX14 gene cause spinocerebellar ataxia, autosomal recessive 20 (SCAR20) in both humans and dogs." (PMID 32792680, 2020). "Mutations in SNX14 cause autosomal recessive spinocerebellar ataxia 20 (SCAR20), a neurodevelopmental disorder characterized by severely delayed psychomotor development with poor or absent speech, absent gait and cerebellar atrophy." (PMID 32377374, 2020). "Mutations in the SNX14 gene cause autosomal recessive spinocerebellar ataxia 20 (SCAR20), characterized by cerebellar atrophy, motor ataxia, and intellectual disability." (PMID 41277110, 2026).
Intellectual disability (8 papers, 2014 to 2024). "To shed light on the cellular and molecular mechanisms that lead to cerebellar degeneration and intellectual disability in SNX14 deficiency, we generated the first Snx14 full-body KO mouse (Snx14-KO) that survives to adulthood." (PMID 38625743, 2024). "SNX14 loss-of-function mutations were identified in patients with cerebellar atrophy, intellectual disabilities and autism, which suggests a critical role of SNX14 in brain function." (PMID 34691693, 2021). "Given that intellectual disability is also a hallmark of SCAR20, we wondered whether Snx14-KO mice had broader behavioral deficits." (PMID 38625743, 2024). "Mutations in Sorting Nexin 14 (SNX14) are the cause of a childhood-onset ataxia known as Spinocerebellar Ataxia Recessive 20 (SCAR20), characterized by progressive cerebellar degeneration and severe intellectual disability." (PMID 38625743, 2024). "The intellectual disability seen in humans with SNX14 mutations was also not identified in the HVs with CCD, although this is challenging to objectively evaluate in dogs and may have developed at a later age." (PMID 27566131, 2016).
Cerebellar atrophy (7 papers, 2018 to 2026). Cerebellar atrophy is defined as a cerebellum with initially normal structures, in a posterior fossa with normal size, which displays enlarged fissures (interfolial spaces) in comparison to the foliae secondary to loss of tissue. "Reduced levels of hydrolytic enzymes and mislocalized lysosomes have been observed in CLN3-mutant cells, and engorged lysosomes were described in SNX14 mutants, causing cerebellar atrophy in humans." (PMID 35351824, 2022).
autosomal recessive cerebellar ataxia (3 papers, 2016 to 2021). "SNX14 is involved in maintaining normal neuronal excitability and synaptic transmission, and a mutation has recently been found to cause autosomal recessive cerebellar ataxia and intellectual disability syndrome in humans." (PMID 27566131, 2016). "Mutations in SNX14 have been reported to cause autosomal recessive cerebellar ataxia and intellectual disability syndrome in humans." (PMID 27566131, 2016).
intellectual disability syndrome (3 papers, 2016 to 2021). "Specifically, mutations in SNX14 were shown to underlie a distinctive autosomal-recessive cerebellar ataxia and intellectual disability syndrome." (PMID 33931804, 2021). "Moreover, SNX14 was shown to associate with an intellectual disability syndrome, being involved in synaptic excitability, among others." (PMID 33931804, 2021).
Anxiety (2 papers, 2016 to 2021). Intense feelings of nervousness, tension, or panic often arise in response to interpersonal stresses. "SNX14 has also been shown to associate with the serotonin subtype 6 receptor, which has been implicated in cognition, anxiety and learning and memory disorders, with SNX14 acting as a negative regulator." (PMID 27566131, 2016).
cerebellar degeneration (2 papers, 2021 to 2024). Degeneration of the cerebellum. "Guided by transcriptomic analyses that pointed to lipid dysregulation as a potential cause of selective cerebellar degeneration, we identify tissue-specific alterations of lipid profiles in Snx14-KO mice." (PMID 38625743, 2024). "Future studies will investigate if the loss of SNX14 affects lipid homeostasis in glia and whether this contributes to the selective cerebellar degeneration in SNX14 deficiency." (PMID 38625743, 2024). "Unlike SCAR20 patients who show severe gait abnormalities typical of cerebellar degeneration, Snx14-KO mice were undistinguishable from their WT littermates based on their home cage walking activity." (PMID 38625743, 2024). "Our study revealed that HP-β-CD, a potential therapy for NPC, failed to ameliorate cerebellar degeneration in Snx14-deficient mice, which suggests that SNX14 deletion may lead to Purkinje cell degeneration through a cholesterol-independent mechanism." (PMID 34691693, 2021). "The present study discovered an unidentified convergence of SNX14 and spastin in mitochondrial transport and dysfunction and demonstrated the possibility of the restoration of mitochondrial function by targeting of the pathway in the treatment of cerebellar degeneration." (PMID 34691693, 2021).
bipolar disorder (1 paper, 2014). A disorder of the brain that causes unusual shifts in mood, energy, activity levels and the ability to carry out day-to-day tasks. "For example, dysregulation of SNX14 has been suggested to occur in bipolar disorder and 6q14 microdeletion syndrome." (PMID 24859318, 2014).
bone osteosarcoma (1 paper, 2021). A usually aggressive malignant bone-forming mesenchymal neoplasm arising from the bone. "SNX14 localizes at the interface between the ER and lipid droplets (LDs); SNX14, overexpressed in human bone osteosarcoma epithelial cells (U2OS), mediates LD budding and growth from the ER surface, after which the LDs are released following its maturation." (PMID 33652569, 2021).
Cognitive impairment (1 paper, 2020). Abnormal cognition is characterized by deficits in thinking, reasoning, or remembering. "Overall, this study allowed to extend the knowledge of the phenotypic and mutational spectrum of SCAR20, and to validate the role of Sorting nexin-14 in a well-defined neurodevelopmental syndrome, which can lead to cognitive impairment." (PMID 33193593, 2020).
proteinopathy (1 paper, 2020). "Thus, Myr could possibly enhance SNX14 to induce autophagy and lipid consumption, and it may upregulate HIGD1a to reduce the oxidative stress caused by proteinopathy and lipid accrual in infected CF cells." (PMID 32781626, 2020).
cancer (1 paper, 2025). A tumor composed of atypical neoplastic, often pleomorphic cells that invade other tissues. "Future research should focus on functional characterization of VUS in genes like SIL1, SNX14, and ALOX12B to elucidate their potential role in cancer pathways." (PMID 41229501, 2025).
infection (1 paper, 2020). The state of being infected such as from the introduction of a foreign agent such as serum, vaccine, antigenic substance or organism. "The expression of both SNX14 and TMEM59 was enhanced by Myr upon infection, suggesting that the compound drives a pathogen-clearance-related autophagy." (PMID 32781626, 2020).
tumor (1 paper, 2020). "Altogether we would consider aberrations in SNX14, SYNCRIP, CBR3-AS1, and CKAP2 as putatively responsible for tumor development or being at least an important passenger aberration in the respective 1N patients." (PMID 32577795, 2020).
SNX14 also shares sentences with these, for which no sentence is quoted: cerebellar ataxia (8 papers); Vici syndrome (3); hereditary spastic paraplegia (2); neurological disorder (2); ataxia telangiectasia (1); autism (1); Bloom syndrome (1); Cerebellar hypoplasia (1); developmental delay (1); inherited diseases (1); movement disorder (1); Spastic paraplegia (1).